RANBP3L (RAN binding protein 3 like)
Description:
Nuclear export factor for BMP-specific SMAD1/5/8 that plays a critical role in terminating BMP signaling and regulating mesenchymal stem cell differentiation by blocking osteoblast differentiation to promote myogenic differention. Directly recognizes dephosphorylated SMAD1/5/8 and mediates their nuclear export in a Ran-dependent manner.
Synonyms: FLJ25422
Tractability: No criterion of Open Targets' tractability assessment is met for any kind of drug.
Gene: Protein-coding gene on chromosome 5 (36,246,913 to 36,302,114, reverse strand). Ensembl gene ENSG00000164188.
Subcellular location: Nucleus; Cytoplasm
Subcellular location (Human Protein Atlas): Nucleoplasm; Cytosol
Gene Ontology:
Molecular function: protein binding; SMAD binding
Biological process: mesenchymal cell differentiation involved in bone development; negative regulation of osteoblast differentiation; positive regulation of myoblast differentiation; protein export from nucleus
Cellular component: nuclear pore; cytoplasm; nucleus
Genetic constraint (gnomAD): Loss-of-function variants: 22 observed, 26.06 expected, observed/expected ratio (o/e) 0.84, 90% interval 0.6 to 1.21. The upper end of that interval is the gene's LOEUF score, 1.21, which puts it in group 5 of 6, group 1 being the genes least tolerant of losing a copy. Missense variants: 228 observed, 246.77 expected, observed/expected ratio (o/e) 0.92, 90% interval 0.83 to 1.03. Synonymous variants: 74 observed, 90.64 expected, observed/expected ratio (o/e) 0.82, 90% interval 0.68 to 0.99.
Homologues: Orthologues: chimpanzee RANBP3L (99% identical), macaque RANBP3L (93% identical), dog RANBP3L (79% identical), rabbit RANBP3L (75% identical), pig RANBP3L (75% identical), mouse Ranbp3l (71% identical), rat Ranbp3l (67% identical), guinea pig RANBP3L (65% identical), tropical clawed frog ranbp3l (36% identical). Paralogues in human: RANBP3 (36% identical), RANBP2 (24% identical), RGPD1 (16% identical), RGPD2 (16% identical), RGPD4 (16% identical), RGPD5 (16% identical), RGPD6 (16% identical), RGPD8 (16% identical), RGPD3 (16% identical), RANBP1 (9% identical).
Diseases named in the same sentence as RANBP3L in open-access papers:
RANBP3L is named in the same sentence as 16 diseases in open-access papers, as found by Europe PMC text mining. Sharing a sentence is not in itself a finding about the gene and the disease. The quoted sentences say what the papers report.
renal carcinoma (2 papers, 2021 to 2023). A carcinoma arising from the epithelium of the renal parenchyma or the renal pelvis. "Loss of RANBP3L expression was found to be associated with loss of epithelial differentiation and induced cell migration behavior in renal cancer cells." (PMID 36672708, 2023). "We show that the expression of Ranbp3l is induced by NFAT5 under hyperosmotic conditions and that the loss of RANBP3L induces the transformation towards a renal cancer cell like phenotype, especially KIRC." (PMID 34233711, 2021).
alcoholism (1 paper, 2019). "The involvement of RANBP3L in schizophrenia has yet to be reported, but exon microarray analysis of human dorsolateral prefrontal cortex revealed up-regulation of this gene in alcoholism." (PMID 30967896, 2019).
breast carcinoma (1 paper, 2023). "Higher expression of RANBP3L was significantly associated with breast cancers with lower histopathological grades (p-value 0.038)." (PMID 36672708, 2023). "For RANBP3L, to our knowledge, this is the first study to examine the mRNA and protein expression of RANBP3L in breast cancer clinical samples." (PMID 36672708, 2023). "Survival analyses in the present study revealed that loss of RANBP3L, GLYATL-1, ESR1, and SFXN2 was significantly related to lower RFS in breast cancer (p-value < 0.012, 1.1 × 10−6, 1 × 10−16, and 1.3 × 10−10, respectively)." (PMID 36672708, 2023). "The expression level of RANBP3L was examined in 74 breast carcinoma tissue sections." (PMID 36672708, 2023). "Thus, we selected RANBP3L and GLYATL-1 to compare the expression of their encoded proteins in breast carcinoma tissue samples and determine the relationship between the expression of the proteins and the age of breast cancer patients." (PMID 36672708, 2023). "The TCGA data showed that young-age breast cancer patients have a lower level of expression of RANBP3L, GLYATL-1, and ESR1, whereas ACVR2A, SERPINE2, and PCDHGB7 have higher expression in young-age breast cancer patients compared to old age patients." (PMID 36672708, 2023).
breast tumors (1 paper, 2023). "On the other hand, a significant association was found between the high expression of RANBP3L and breast tumors with a low histopathological grade (Modified Bloom Richardson Grade I)." (PMID 36672708, 2023).
clear cell carcinoma (1 paper, 2021). "Strikingly, a RANBP3L dependent signature of 60 genes separated samples with clear cell carcinoma (KIRC) from papillary (KIRP), chromophobe renal carcinoma (KICH) and healthy tissue." (PMID 34233711, 2021).
endometrial cancer (1 paper, 2026). Primary or metastatic malignant neoplasm involving the endometrium (mucous membrane that lines the endometrial cavity). "There are little researches about RANBP3L in tumors, only one report shows that the immune cell enrichment score of RANBP3L combined with other seven genes can predict outcomes in endometrial cancer patients." (PMID 41457788, 2026).
glioma (1 paper, 2024). A benign or malignant brain and spinal cord tumor that arises from glial cells (astrocytes, oligodendrocytes, ependymal cells). "No data on the involvement of such genesas ASCC1, ZCCHC17 (participates in biogenesisof ribosomal DNA), PLAT, CISD1,TMEM229a and RANBP3L in the development and spread ofany glioma types have been found." (PMID 39539523, 2024).
hepatocellular carcinoma (1 paper, 2026). A malignant tumor that arises from hepatocytes. "This study aimed to explore the pan‐cancer expression, prognostic value, and immune‐related roles of RANBP3L, especially emphasis on validating its diagnostic and prognostic significance in hepatocellular carcinoma." (PMID 41457788, 2026).
Hypertension (1 paper, 2017). The presence of chronic increased pressure in the systemic arterial system. "Genetic analyses have identified suggestive associations near RANBP3L with height, hypertension, and serum tamsulosin hydrochloride concentration." (PMID 28417008, 2017).
tumor (4 papers, 2017 to 2026). "Functional analysis of RANBP3L-deficient cells revealed a loss of epithelial structure, an increased cell migration behavior and colony forming capacity, accompanied by massive alterations in gene expression, all of which are hallmarks for tumor cells." (PMID 34233711, 2021). "Loss of RANBP3L induces a tumor like phenotype resembles RCC, especially KIRC, on the morphological and gene expression level and might promote tumor development and progression." (PMID 34233711, 2021). "Together, loss of RANBP3L induces transformation towards a tumor cell-like phenotype." (PMID 34233711, 2021). "Since RANBP3L-KO cells showed morphological changes towards a fibroblast-like phenotype, which represents a hallmark of tumor cell migration, we analyzed if loss of Ranbp3l expression also affects functional parameters like cell migration, proliferation and colony forming capability." (PMID 34233711, 2021). "In 18 different cancers, RANBP3L expression was found to be lower in tumor tissues compared to normal tissues, including LIHC." (PMID 41457788, 2026). "The RANBP3L expression was significantly related to pathologic M stage, tumor status, AFP (ng/mL), and histologic grade in LIHC." (PMID 41457788, 2026). "Among these 23 cancers, RANBP3L expression was reduced in tumor tissues compared to normal tissues in 14 cancers, including LIHC, KIRC, LUAD, and so on." (PMID 41457788, 2026). "Among these 33 cancers, RANBP3L expression was reduced in tumor tissues compared to normal tissues in 18 cancers, including LIHC, KIRC, LUAD, and so on." (PMID 41457788, 2026). "Furthermore, analysis of LIHC patient tissues found that higher RANBP3L expression was related to better tumor‐free survival and OS." (PMID 41457788, 2026). "The results showed that RANBP3L might function as a candidate tumor suppressor and the function of tumor suppressor may be achieved through regulating BMP‐driven lineage‐specific differentiation of mesenchymal stem cells." (PMID 41457788, 2026).
cancer (3 papers, 2021 to 2026). A tumor composed of atypical neoplastic, often pleomorphic cells that invade other tissues. "In this research, we assessed the diagnostic and prognostic value of RANBP3L in pan‐cancer, especially in liver hepatocellular carcinoma (LIHC)." (PMID 41457788, 2026). "RAN binding protein 3‐like (RANBP3L), a member of the Ran‐binding protein family, has been linked to various cellular functions, but the role in cancer remains underexplored." (PMID 41457788, 2026). "Among the 33 cancers, the RANBP3L expression was linked to the LIHC patients' OS and DSS and further correlated with AFP levels and pathological grade." (PMID 41457788, 2026). "Therefore, we investigated the diagnostic and prognostic value of RANBP3L specifically in this cancer type, for which ROC analysis and a nomogram model were subsequently established based on its expression in LIHC." (PMID 41457788, 2026). "For KIRC, LIHC and LUAD, lower RANBP3L expression in cancer tissues was associated with poorer DSS." (PMID 41457788, 2026). "Besides functional differences, loss of RANBP3L is accompanied by a massive shift towards a gene expression profile that is linked to different cancer-associated pathways including the phosphatidylinositol 3 kinase (PI3K)/Akt, EMT or TGF-β signaling cascades." (PMID 34233711, 2021). "In conclusion, we could show that the osmoregulatory NFAT5 directly drives Ranbp3l expression and that loss of RANBP3L leads to a cancer promoting phenotype associated with human RCC, predominantly the KIRC subtype." (PMID 34233711, 2021). "For cancers that the RANBP3L expression was related to patients' prognosis, the connection between RANBP3L expression and patients' clinical profiles was further analyzed, according to the TCGA database." (PMID 41457788, 2026). "CIBERSORT analysis showed that in some cancer types, a relationship was observed between the levels of immune cell infiltration and RANBP3L expression." (PMID 41457788, 2026). "For STAD and UCEC, the higher RANBP3L expression in cancer tissues indicated worse DSS, respectively." (PMID 41457788, 2026). "RANBP3L expression for un‐paired samples was displayed in 33 cancers according to the TCGA database." (PMID 41457788, 2026). "We analyzed the expression trends and prognostic relevance of RANBP3L across multiple cancers, particularly focusing on LIHC to find the role of RANBP3L in the LIHC progress." (PMID 41457788, 2026). "For LIHC patients, the lower expression of RANBP3L in cancer tissues indicated worse OS, respectively." (PMID 41457788, 2026). "We analyzed RANBP3L expression of 33 cancer types from TCGA data and assessed its relationship with overall survival (OS), disease‐specific survival (DSS), and progression‐free interval (PFI)." (PMID 41457788, 2026). "Based on these data, we propose that RANBP3L is a crucial regulator of epithelial integrity in renal cells and that its functional can promote cancer development and/or progression." (PMID 34233711, 2021). "For STAD and UCEC, the higher RANBP3L expression in cancer tissues means worse PFI." (PMID 41457788, 2026). "For KIRC, the lower RANBP3L expression in cancer tissues means worse PFI." (PMID 41457788, 2026). "Similarly, the expression of RANBP3L for paired samples was also found in 23 cancers according to the TCGA database." (PMID 41457788, 2026). "RANBP3L expression was elevated in para‐carcinoma tissues in comparison with LIHC tissues." (PMID 41457788, 2026). "Xenograft based studies of RANBP3L-KO mpkCCD cells and KIRC cell lines would give us more information regarding cancer growth and metastasis." (PMID 34233711, 2021). "Although all RCC subtypes share low levels of RANBP3L, higher expression positively correlates with overall survival in KIRC but not in KICH and KIRP suggesting RANPB3L downregulation as major KIRC-specific feature during cancer progression." (PMID 34233711, 2021).
RANBP3L also shares sentences with these, for which no sentence is quoted: Alzheimer disease (2 papers); hypothyroidism (1); liver cancer (1); renal clear cell carcinoma (1); schizophrenia (1).